FNTA (farnesyltransferase, CAAX box, subunit alpha)
Description:
Essential subunit of both the farnesyltransferase and the geranylgeranyltransferase complex. Contributes to the transfer of a farnesyl or geranylgeranyl moiety from farnesyl or geranylgeranyl diphosphate to a cysteine at the fourth position from the C-terminus of several proteins having the C-terminal sequence Cys-aliphatic-aliphatic-X. May positively regulate neuromuscular junction development downstream of MUSK via its function in RAC1 prenylation and activation.
Synonyms: FPTA; PGGT1A; PTAR2
Tractability: Small molecule: an approved drug acts on it; a structure with a bound ligand is known; a high-quality ligand is known; it has a binding pocket of medium quality; it belongs to a druggable protein family. Antibody: its Gene Ontology location is reachable by antibodies, with medium confidence. PROTAC: ubiquitination databases record sites on it; its protein half-life has been measured; a small molecule that binds it is known.
Target class: Enzyme; Transferase
Gene: Protein-coding gene on chromosome 8 (43,034,194 to 43,085,788, forward strand). Ensembl gene ENSG00000168522.
Subcellular location (Human Protein Atlas): Cytosol
Pathways (Reactome):
Disease: Potential therapeutics for SARS
Immune System: GBP-mediated host defense
Programmed Cell Death: Apoptotic cleavage of cellular proteins
Sensory Perception: Inactivation, recovery and regulation of the phototransduction cascade
Signal Transduction: RAS processing
Gene Ontology:
Molecular function: acetyltransferase activator activity; alpha-tubulin binding; enzyme binding; microtubule binding; molecular adaptor activity; protein binding; protein farnesyltransferase activity; protein geranylgeranyltransferase activity; CAAX-protein geranylgeranyltransferase activity; protein prenyltransferase activity; Rab geranylgeranyltransferase activity; receptor tyrosine kinase binding
Biological process: protein farnesylation; protein geranylgeranylation; regulation of microtubule-based movement; peptide pheromone maturation; transforming growth factor beta receptor signaling pathway; CAAX-box protein maturation; enzyme-linked receptor protein signaling pathway; neuromuscular junction development; positive regulation of Rac protein signal transduction; skeletal muscle acetylcholine-gated channel clustering
Cellular component: CAAX-protein geranylgeranyltransferase complex; microtubule associated complex; protein farnesyltransferase complex; cytoplasm; cytosol; plasma membrane
Genetic constraint (gnomAD): Loss-of-function variants: 9 observed, 10.98 expected, observed/expected ratio (o/e) 0.82, 90% interval 0.49 to 1.42. The upper end of that interval is the gene's LOEUF score, 1.42, which puts it in group 5 of 6, group 1 being the genes least tolerant of losing a copy. Missense variants: 224 observed, 177.98 expected, observed/expected ratio (o/e) 1.26, 90% interval 1.13 to 1.41. Synonymous variants: 91 observed, 75.57 expected, observed/expected ratio (o/e) 1.2, 90% interval 1.01 to 1.43.
Homologues: Orthologues: chimpanzee FNTA (99% identical), rat Fnta (93% identical), mouse Fnta (92% identical), guinea pig FNTA (91% identical), pig FNTA (91% identical), tropical clawed frog fnta (70% identical), zebrafish fnta (59% identical), Drosophila melanogaster Fnta (41% identical), Caenorhabditis elegans fnta-1 (32% identical). Paralogues in human: RABGGTA (21% identical), PTAR1 (19% identical).
Diseases named in the same sentence as FNTA in open-access papers:
FNTA is named in the same sentence as 13 diseases in open-access papers, as found by Europe PMC text mining. Sharing a sentence is not in itself a finding about the gene and the disease. The quoted sentences say what the papers report.
schizophrenia (2 papers, 2020). A major psychotic disorder characterized by abnormalities in the perception or expression of reality. "Accordingly, we assayed protein expression of the prenyltransferases subunits FNTA, FNTB, PGGT1B, RABGGTA, and RABGGTB in DLPFC from schizophrenia and matched comparison subjects." (PMID 32066669, 2020). "To test this, we assayed protein expression of the five prenyltransferase subunits (FNTA, FNTB, PGGT1B, RABGGTA, and RABGGTB) in postmortem dorsolateral prefrontal cortex from patients with schizophrenia and paired comparison subjects (n = 13 pairs)." (PMID 32066669, 2020). "We found decreased levels of FNTA (14%), PGGT1B (13%), and RABGGTB (8%) in schizophrenia." (PMID 32066669, 2020). "In summary, we found decreased protein expression of the prenyltransferase subunits FNTA, PGGT1B, and RABGGTB in schizophrenia DLPFC as well as evidence from a bioinformatic analysis of differential gene expression of prenylation-associated genes across multiple brain regions and cortical layers." (PMID 32066669, 2020). "We found protein expression of FNTA, PGGT1B, and RABGGTB prenyltransferase subunits decreased in schizophrenia DLPFC relative to paired comparison subjects, changes not likely due to chronic antipsychotic treatment." (PMID 32066669, 2020).
Coronary Artery Disease (1 paper, 2025). "For Coronary Artery Disease (CAD), five genes intersected between RFE and DEA analyses: CSNK1A1, AKAP5, TOPORS, ACTBL2, and FNTA." (PMID 40287491, 2025).
ovarian carcinoma (1 paper, 2024). A malignant neoplasm originating from the surface ovarian epithelium. "By screening 31 drugs with 110 targets, FNTA, HSPA5, NEU1, CCND1, CASP1, CASP3 were negatively correlated with ovarian cancer, and HMGCR, PLA2G4A, ITGAL, PTGS1, FNTB were positively correlated with ovarian cancer." (PMID 38651149, 2024). "Among them, FNTA, HSPA5, NEU1, CCND1, CASP1, CASP3 had a negative causal association with ovarian cancer development, and HMGCR, PLA2G4A, ITGAL, PTGS1, FNTB had a positive causal association with ovarian cancer development." (PMID 38651149, 2024).
cancer (6 papers, 2015 to 2026). A tumor composed of atypical neoplastic, often pleomorphic cells that invade other tissues. "Compared to S100A10, presently much fewer studies explore the relations between FCER1A, FNTA, and cancer." (PMID 36430822, 2022). "FTase proteins (FNTA and FNTB) as well as eight of the 116 PFPs are known cancer-relevant proteins as per COSMIC Cancer Gene Census49 or TCGA50 (KRAS, HRAS, NRAS, RHEB, RHOA, DDX3X, ARID2, and SAV1)." (PMID 39995872, 2025). "On the opposite side, the roles of FCER1A and FNTA in cancer and therapeutic resistance have not been well studied and thus could be novel markers of therapeutic resistance in CML." (PMID 36430822, 2022).
FNTA also shares sentences with these, for which no sentence is quoted: infection (4 papers); breast carcinoma (1); diabetic retinopathy (1); lung carcinoma (1); pancreatic endocrine tumors (1); rhabdomyosarcoma (1); tularemia (1); tumor (1); urinary tract infection (1).